Y_RNA (Y RNA )
Gene: Miscellaneous RNA gene on chromosome 9 (96,103,079 to 96,103,174, reverse strand). Ensembl gene ENSG00000201938.
Homologues: Orthologues: chimpanzee Y_RNA (93% identical), macaque Y_RNA (90% identical). Paralogues in human: RNY4 (85% identical), RNY4P7 (84% identical), RNY4P24 (83% identical), RNY4P3 (82% identical), RNY4P37 (82% identical), RNY4P6 (82% identical), Y_RNA (82% identical), Y_RNA (81% identical), RNY4P10 (80% identical), RNY4P14 (80% identical), RNY4P17 (80% identical), RNY4P19 (80% identical), and 90 more.